FOXC2 (forkhead box C2)
Diseases named in the same sentence as FOXC2 in open-access papers (continued):
Sharing a sentence is not in itself a finding about the gene and the disease.
pharynx tumors (1 paper, 2015). "Interestingly, we noticed upregulation of BCL2L11, the known apoptotic pathway gene, in the larynx tumors and downregulation of FOXC2 gene, involved in EMT pathway, in the pharynx tumors only." (PMID 25575813, 2015).
renal cell carcinoma (1 paper, 2018). "Samples (n = 62) were evaluated from the tumors of patients with renal cell carcinoma; 80% of cancerous renal tissue samples were positive for FOXC2 expression." (PMID 30279969, 2018).
Sepsis (1 paper, 2021). Sepsis is defined as life-threatening organ dysfunction caused by a dysregulated host response to infection. "We postulated that FOXC2 regulates its own expression in sepsis, and its transcriptional autoregulation directs lymphatic EC cell-fate decision." (PMID 34017833, 2021). "Collectively, using human lung EC, as well as a sterile sepsis model in neonatal mice, we demonstrate that FOXC2 regulates its own expression through a histone acetylation- dependent positive feedback loop during TLR4 stimulation in developing lung EC." (PMID 34017833, 2021). "In a neonatal mouse model of sterile sepsis, LPS-induced FOXC2 binding to FBE and FOXC2 expression in lung EC was attenuated with garcinol treatment." (PMID 34017833, 2021). "In this study, we hypothesized that FOXC2 expression is self-regulated by FOXC2 transcriptional activation and its binding affinity to FBE is regulated by histone acetylation during sepsis." (PMID 34017833, 2021).
speech language disorder (1 paper, 2015). "For example, the R553H mutation in FOXP2 (equivalent to FOXM1 R286) is associated with development of a severe speech language disorder, while a mutation of the same arginine residue in FOXC2 (R121C) is associated with a developmental disorder affecting the lymphatic vasculature system." (PMID 26100407, 2015).
tooth agenesis (1 paper, 2022). A tooth disease characterized by failure to develop one or more missing teeth. "FOXC2 is also predicted to positively regulate LAMC2 and MSX1, a highly conserved transcription factor well-known to regulate tooth formation, and causing tooth agenesis in humans when mutated." (PMID 35217915, 2022).
cancer (102 papers, 2012 to 2025). A tumor composed of atypical neoplastic, often pleomorphic cells that invade other tissues. "FOXC2 is linked to poor prognoses across various cancer types and is notably upregulated in TNBC, where it establishes and sustains these stem-like cells within the tumor population." (PMID 40227590, 2025). "A transcription factor known as FOXC2, which plays an important role in determining the fate of mesenchymal cells during embryonic development, has also been implicated in cancer cells’ ability to metastasize." (PMID 37999477, 2023). "The upregulated EMT-inducers—Zeb2, Foxc2 and Inhba—have also been implicated in promoting cancer stem-cell and metastatic properties." (PMID 32581213, 2020). "In univariate survival analyses of Gleason score 7 patients, strong FOXC2 expression was significantly associated with clinical recurrence (p = 0.047), skeletal metastasis (p = 0.011) and cancer‐specific survival (p = 0.006)." (PMID 31464093, 2019). "Often, increased expression of FOXC2 during EMT is associated with highly-metastatic cancers, some of which can be reduced by shRNA therapy." (PMID 31080560, 2019). "In univariate survival analyses including all 338 patients from series 1, strong FOXC2 expression was borderline associated with shorter time to clinical recurrence (p = 0.073), skeletal metastasis (p = 0.081), and cancer specific death (p = 0.069)." (PMID 31464093, 2019). "It has been shown that elevated FOXC2 expression is associated with increased metastasis in several cancer types, including breast, colorectal, nasopharingeal and esophageal." (PMID 27634875, 2016). "FOXC2 has also recently emerged as a potential biomarker linked to the progression of several cancers and is associated with tumor cell proliferation, drug resistance, and initiation of the epithelial-mesenchymal transition (EMT) that takes place before cancer cell invasion and metastasis." (PMID 39473610, 2024). "Further, whether exaggerated FOXC2 autoregulation underlies FOXC2’s role in cancer remains to be determined." (PMID 34017833, 2021). "In univariate survival analyses of the clinically important, large subgroup of 199 patients with Gleason score 7, high FOXC2 expression and EN‐switching were significantly associated with shorter time to clinical recurrence, skeletal metastases and cancer specific death." (PMID 31464093, 2019). "LDS patients carrying FOXC2 gain of function mutations should be carefully monitored in order to verify whether they present an higher cancer susceptibility and to ensure the earliest identification of possible lesions." (PMID 27276711, 2016). "We also considered the analysis of recurrence of cancer, and we found that the level of gene expression in the normal tissue was associated with recurrence for many genes: FOXC2, CDC20, OCLN and SERPINB2 (p = 0.0067, p = 0.0067, p = 0.048 and p = 0.0352 respectively)." (PMID 25575813, 2015). "FOXC2 expression levels were reduced upon β-catenin knockdown, suggesting that FOXC2 expression in the EMT-enriched cancer cells is dependent on β-catenin." (PMID 40227590, 2025). "As a critical regulator of tumor progression, FOXC2 has become a valuable biomarker for predicting cancer aggressiveness and patient prognosis." (PMID 40746552, 2025). "EMT can begin when any of the EMT inducers, such as Twist, TGF‐β1 or Snail, are overexpressed because it increases the expression of FOXC2 As cancer progresses, there is a noticeable cadherin flip from E‐ to N‐cadherin." (PMID 40159638, 2025). "To understand the clinical implications of the β-catenin/FOXC2 signaling pathway, we examined the EMTome, a public resource for cancer dataset analysis, to assess the correlation between FOXC2 and β-catenin in cancer patients across various carcinoma types." (PMID 40227590, 2025). "While FOXC1 and FOXC2 are often upregulated in multiple human cancers to drive EMT and metastasis, their downregulation in late FDIM suggests an alternative mechanism in tumorigenesis." (PMID 40683913, 2025).
cancer (continued). "Taking cues from our understanding of FOXC2’s regulation during development can help to determine its role and regulation in cancer progression." (PMID 40227590, 2025). "The activation of the embryonic program known as epithelial–mesenchymal transition, which is mediated by the transcription factor FOXC2, generates these cancer stem cells." (PMID 40227590, 2025). "Recent investigations have begun to elucidate FOXC2’s role in cancer progression, with studies demonstrating its involvement in promoting EMT, vasculogenic mimicry, and resistance to anti-angiogenic therapy in triple-negative breast cancer." (PMID 40781106, 2025). "Understanding the regulation and activation of FOXC2 during cancer progression will guide the development of therapeutics that can eradicate the cancer stem cell population." (PMID 40227590, 2025). "Collectively, the TCGA and EMTome data extend and further support the notion that FOXC2 and β-catenin are predominantly co-active in aggressive carcinomas in patient samples." (PMID 40227590, 2025). "With FOXC2 proposed as a potential therapeutic target for cancer metastasis, its pleiomorphic downstream systemic effects should be considered against the increased chance of developing nonhealing or slow-to-heal wounds." (PMID 39473610, 2024). "Since chronic lymphedema is a forerunner of several malignancies and cancers have been known to arise from poorly healing chronic wounds (e.g., Marjolin ulcers), we examined the effect of Foxc2 dysfunction on skin wound healing." (PMID 39473610, 2024). "Further studies have identified a link between PDGFRβ expression in TNBC, and cancer stem cells, where FOXC2 induces cancer stem cell characteristics and metastasis by upregulating PDGFRβ expression." (PMID 38699644, 2024). "Tumors that are affected by vasculogenic mimicry are also difficult to treat as they are resistant to anti-angiogenic therapies, so suppressing FOXC2 would allow for the cancers to be more receptive to treatments." (PMID 39698202, 2024). "Because we found that FOXC2, which is tied to cancer metastasis and lymphatic dysregulation, also impairs wound healing and promotes fibrotic tissue architecture, future work should also investigate the connection between these disease states." (PMID 39473610, 2024). "With FOXC2 proposed as a potential therapeutic target for cancer metastasis, its downstream systemic effects should be considered against the increased chance of developing nonhealing wounds." (PMID 39473610, 2024). "Here, we found that FOXC2, which is tied to cancer metastasis and lymphatic dysregulation, also impairs wound healing and promotes "brotic tissue architecture." (PMID 39473610, 2024). "Based on previous studies highlighting the importance of FOXC2 in cancer progression, we investigated its potential interaction with LINC02159." (PMID 39657309, 2024). "In the case of cancer, dysregulation of insulin signaling and overexpression of transcription factor FOXC2 are related to promoting tumor proliferation and migration." (PMID 39344752, 2024). "Prior to our work, the most established role for FOXC2 in cancer was as an EMT regulator and in metastasis." (PMID 37499655, 2023). "Angiogenesis, invasion, metastasis, invasion of growth eliminators, genomic instability and mutation, and the maintenance of proliferative signals are the primary functions of FOXC1 and FOXC2 in cancer." (PMID 37626655, 2023). "The polyclonal FOXC2 antibody used in that study was primarily expressed in cancer cells although the nuclei of stromal cells also exhibited weak expression." (PMID 36230774, 2022). "In the meantime, research showed that FOXC2 played a core role in cancer, as it was often overexpressed in OC." (PMID 35392966, 2022). "Eighteen days after subcutaneous injection of cancer cells, the FOXC2-expressing cells had formed significantly larger tumors than the GFP-expressing cells." (PMID 36230774, 2022).
cancer (continued). "FOXC2 has been proposed as a potential therapeutic target because it is involved in multiple processes that support cancer growth, metastasis, and chemotherapy resistance, such as EMT, CSC differentiation, angiogenesis, and resistance to anoikis." (PMID 36230774, 2022). "FOXC2 is an oncogene, overexpressed in multiple cancers promoting cell proliferation and inducing epithelial-mesenchymal transition (EMT)." (PMID 35562754, 2022). "FOXC2 is an inducer of EMT, tumor angiogenesis and metastasis, and elevated levels of FOXC2 are associated with advanced cancer and poor prognosis." (PMID 35912113, 2022). "Two of these three samples exhibited focal nuclear FOXC2 staining in cancer cells and contained tubular structures with intraluminal red blood cells lined with FOXC2-expressing cancer cells, which is indicative of VM." (PMID 36230774, 2022). "In our study, only 12% of HGSOC were positive for FOXC2 and the expression was restricted to a small subset of cancer cells." (PMID 36230774, 2022). "In pathological states, FOXC2 overexpression is involved in cancer progression through several mechanisms, including epithelial mesenchymal transition (EMT)." (PMID 34017833, 2021). "FOXC2 is a well-known carcinogenic transcription factor that participates in drug resistance in various cancers." (PMID 33869020, 2021). "Considering that FOXL1 has been extensively studied as a tumor suppressor, we selected FOXC2, a recognized oncogene in multiple cancer types, for further investigation." (PMID 33869020, 2021). "As a member of the C family of FOX proteins, FOXC2 has been reported to play crucial roles in cancer progression, including in chemoresistance." (PMID 33869020, 2021). "Recent studies have demonstrated that FOXC2 is also a crucial regulator of several hallmarks of cancer progression." (PMID 32698337, 2020). "Based on these diverse tumor-promoting functions and the breadth of tumor types in which FOXC2 is dysregulated, it is important to improve our understanding of this transcription factor's regulation of oncogenic pathways in cancer cells." (PMID 32175283, 2020). "The forkhead box protein C2 (FOXC2) transcription factor has recently emerged as a key regulator of tumor progression in many cancer types." (PMID 32175283, 2020). "FOXC2 transcription factor plays an important role in human pathophysiology, both in genetics and in cancer." (PMID 32698337, 2020). "Another DE gene on the list, Forkhead Box C2 (FOXC2), whose overexpression induces hyperphosphorylation of ERK1/2 in cancer cells and is associated with aberrant cell proliferation, also has decreased mRNA expression in the affected individuals." (PMID 32698886, 2020). "The results showed that angiogenesis pathway was the top altered pathway, and FOXC2, a critical transcription factor regulating tumor angiogenesis and inducing epithelial-mesenchymal transition in various cancers, was significantly affected." (PMID 32341351, 2020). "Our data supports previously reported functions of FOXC2 in other cancer types and provides potential molecular insights into the oncogenic activity of this transcription factor." (PMID 32175283, 2020). "FOXC2 was an independent predictor of time to clinical recurrence (HR 1.8, p = 0.023), skeletal metastasis (HR 3.7, p = 0.004) and cancer specific death (HR 4.8, p = 0.001), together with the EN‐switch and Gleason grade groups (GG3 [4+3] versus GG2 [3+4])." (PMID 31464093, 2019). "TWIST1, SNAI2 and FOXC2 also showed moderate inverse correlations with immune cell content in four of five cancer types." (PMID 31780722, 2019). "ZEB1, ZEB2, SNAI1, SNAI2 and FOXC2 exhibited consistent positive correlations with the ESTIMATE stromal score in all five cancer types." (PMID 31780722, 2019). "Patients harbouring cancers with high FOXC2 mRNA expression level showed shorter time to biochemical recurrence (p = 0.006), and a similar result was observed among Gleason score 7 carcinomas (n = 44; p = 0.003)." (PMID 31464093, 2019).
cancer (continued). "FOXC2 appears to be related to cancer aggressiveness, including proliferative marker accumulation and EMT induction/Cadherin switch in HCC." (PMID 29801468, 2018). "Here, we characterized the relationship between FOXC2 and cancer progression by conducting a meta-analysis of studies that reported the frequency of FOXC2 expression in tumors of different stages (T1, T2, T3, T4)." (PMID 30279969, 2018). "FOXC2 also influences cancer growth and progression by acting as a mediator of both angiogenesis and lymphangiogenesis." (PMID 30279969, 2018). "The study indicates that Foxc2 is a signal of canonical Wnt pathway in mouse P19 embryonal carcinoma cells." (PMID 30147726, 2018). "We also detected upregulation of genes involved in cancer metastasis and cancer stemness (FOXC2, SNAI2, CXCRs, and IGF1), cell stemness (NANOG, POU5F1, and KLF4), metalloproteinases (MMP7, MMP10, and MMP13), and angiogenic factors (IL-8 and S1PR1)." (PMID 28423353, 2017). "FOXC2 has been demonstrated not only to be involved in epithelial-mesenchymal transition (EMT) but also contributes to stem cell properties in cancer cells." (PMID 28445151, 2017). "FOXC2, previously known to be involved in specifying mesenchymal cell fate during embryogenesis, was identified as an EMT-inducing TF that associates with cancer metastasis by the Weinberg group." (PMID 25216525, 2014). "Although FOXC2 protein has a cytoplasmic localization in cancer cells, our immunohistochemistry results showed that FOXC2 is detectable in the nuclei of cancer cells." (PMID 24647631, 2014). "Furthermore, we observed that multiple aggressive cancer types have high levels of β-catenin and FOXC2." (PMID 40227590, 2025). "However, this study was focused on cellular differentiation during mitogenesis, while our study is focused on understanding the role of FOXC2/β-catenin in EMT, which is implicated in cancer progression and metastasis." (PMID 40227590, 2025). "Remarkably, the mere activation of Wnt/ERK/CDK4/6 in E/M cells suffices to cement a programme integrating cancer stem cell maintenance (via FOXC2/p63) and self-renewal (via S-phase and FOXM1 activation) with inhibition of differentiation (via EGFR inactivation)." (PMID 40764669, 2025). "Moreover, there is a positive correlation between the expression of β-catenin and FOXC2 in various cancer subtypes observed in clinical patient samples." (PMID 40227590, 2025). "In addition to MMPs, there was higher expression of Foxc2, a transcription factor associated with EMT and cancer metastasis, and stemness marker Lgr5." (PMID 37581937, 2023). "Moreover, FOXC2-target genes were upregulated in VM-proficient human cell lines from the Cancer Cell Line Encyclopedia (CCLE) at the mRNA and protein level." (PMID 37499655, 2023). "Like FOXC1, FOXC2 plays a significant part in the evolution of different cancer types." (PMID 37626655, 2023). "Importantly, HUVEC migration was completely abolished in the presence of conditioned media from cancer cells in which FOXC2 was knocked down, demonstrating that FOXC2 is a crucial factor in cancer cell-mediated angiogenesis." (PMID 36230774, 2022). "In addition to the well-documented paracrine effects of FOXC2 on endothelial cells, it has been shown that FOXC2-expressing cancer cells are capable of trans-differentiation into endothelial cells." (PMID 36230774, 2022). "Our study confirms the previously recognized roles of FOXC2 in cancer and introduces VM as one of the processes by which FOXC2 could promote cancer progression." (PMID 36230774, 2022). "As the structure of FOXS1 is highly similar with FOXC2, we propose that they may share similarities in their biological functions in human cancers." (PMID 35898871, 2022). "We confirmed most of the known mechanisms by which FOXC2 promotes cancer aggressiveness." (PMID 36230774, 2022). "FOXC2 has also been found to be related to oxidative stress-related pathways in cancer research." (PMID 34858542, 2021).